HGF (hepatocyte growth factor)
Diseases named in the same sentence as HGF in open-access papers (continued):
Sharing a sentence is not in itself a finding about the gene and the disease.
tumor (continued). "HGF and TGF-β are produced by different liver cells and platelets and regulate not only tumor cell fate but also HPCs, inflammation and fibrosis, these being key players in these processes." (PMID 38138981, 2023). "MET was a transmembranous tyrosine kinase receptor (TKR) in hepatocyte growth factor/MET (HGF/MET) pathway, and was well known as its critical role in pathogenesis of tumor." (PMID 36873946, 2023). "During tumor progression, TTSPs such as matriptase, hepsin, and TMPRSS2 activate pro-HGF to elicit the HGF/c-MET pro-oncogenic/cell survival signaling pathway in vivo and/or in vitro." (PMID 37009799, 2023). "By silencing HGF in SGC-7901 cells with siRNA, tumor angiogenesis was also suppressed and VEGF expression was also downregulated." (PMID 37189649, 2023). "In xenograft models, cMet inhibitors (anti-HGF, anti-MET, and MET-targeted small molecule inhibitors) decrease tumour progression and the expression of stem markers such as CD133, Sox2, and Nanog." (PMID 37368660, 2023). "McCarty reported that tumor cell proliferation and invasion are regulated via crosstalk between the VEGF and HGF signaling pathways." (PMID 37835592, 2023). "MSCs secrete a variety of angiogenesis promoting factors, such as VEGF, PDGF, IL-6, IL-8, angiopoietin-1, HGF and BDNF, to improve the regeneration of blood vessels, which is reasonably postulated to promote the tumor growth." (PMID 37957675, 2023). "In this TME, the accumulation of lactate can both increase the expression of HGF in CAFs in an NF-κB-dependent manner and modify the ECM by inducing MMP expression through the ERK/p90RSK pathway in tumor cells." (PMID 37919751, 2023). "HGF secreted in response to CAF irradiation can enhance the phosphorylation activity of c-MET and MAPK in tumor cells, which translates into stronger invasion capacity." (PMID 37607935, 2023). "Meanwhile, Rbfox3 and SFRTM2 levels were downregulated while the levels of the fibrosis markers HGF, HMOX1, ELN, and GREM1 were upregulated in the tumor microenvironment of NEPC." (PMID 37240308, 2023). "HGF acts by stimulating the cMet/Erk1/2/FRA1/HEY1 axis in HCC cells, and fos-related antigen 1 (FRA1) silencing effectively retards HGF-induced tumor growth and metastasis." (PMID 36708970, 2023). "M2 TAMs offer hepatocyte growth factor (HGF) to activate the HGF/c‐Met, ERK1/2/MAPK, and PI3K/AKT pathways, enlisting more macrophages to tumor tissue and intensifying HCC resistance to sorafenib in a pre‐feedback manner." (PMID 38098217, 2023). "The use of capmatinib circumvented entrectinib resistance in a subcutaneous tumor model inoculated with KM12SM and HGF‐producing fibroblasts." (PMID 36416133, 2023). "Another study found that combining ctDNA detection with optimized cutoffs of four tumor markers (CA19-9, CEA, hepatocyte growth factor (HGF), and osteopontin (OPN)) increased sensitivity for PDAC detection sensitivity from 30% to 64% with 99.5% specificity." (PMID 36835649, 2023). "Hepatocyte growth factor (HGF), secreted by CD11b+CD11c+ macrophages, augments tumor cell survival under stress conditions in vitro." (PMID 37443711, 2023). "The HGF/c-MET axis and Hh pathway play critical roles in the interaction between tumor cells and CAFs." (PMID 37919751, 2023). "The recruitment of CAFs by tumors involves the secretion of HGF, which in turn activates downstream signal transduction through C-MET within tumor cells." (PMID 37919751, 2023). "This process is regulated by transcription factors in tumor cells (Snail 1, Slug, ZEB1, Twist, FOXC2, etc.)and signaling pathways from the tumor microenvironment (WNT, Notch, Hedgehog, TGFβ, FGF, EGF, HGF signaling, etc.)." (PMID 38139030, 2023). "Foretinib inhibited the HGF-induced MET phosphorylation and prevented the HGF-induced responses of tumor cells." (PMID 36614199, 2023).
tumor (continued). "In terms of the PSC function, CTHRC1 treatment markedly increased the genetic expression of tumor-promoting growth factors (EGF, HGF, and FGF by 4.9, 4.4, and 10.5 times, respectively) and cytokines (IL8 and IL10 by 3.7 and 2.9 times, respectively)." (PMID 37444482, 2023). "The c-Mesenchymal-epithelial transition factor (c-Met) is a distinct subfamily of receptor tyrosine kinases (RTKs) that is activated solely by hepatocyte growth factor (HGF), and plays a key role in tumor survival, growth, angiogenesis and Metastasis." (PMID 37945598, 2023). "Our results are in agreement with previous reports of intratumoral HGF expression in most lung tumour subtypes, with a strong HGF immunostaining reported in 42 to 70% of NSCLC tumours." (PMID 36799689, 2023). "This review aims to provide an overview of the current understanding of the HGF/c-MET axis and Hh pathway in tumor cells and CAFs, as well as their interaction with each other." (PMID 37919751, 2023). "The MET/HGF pathway can also regulate VEGF expression and promote angiogenesis during tumor progression." (PMID 36831657, 2023). "The autocrine signaling of HGF induced phosphorylation of c-Met, thus activating MAPK, as well as AKT pathways, creates tumor sensitivity to SGX523." (PMID 36080304, 2022). "This instructed CAFs to over-secrete HGF, that activated the MET pathway in tumor cells, thus favoring their escape from MET or EGFR targeting." (PMID 36324182, 2022). "Binding to HGF leads to dimerization and activation of c-MET receptors, which promotes the proliferation, migration, and invasion of tumor cells." (PMID 35874635, 2022). "HGF/c-MET signalling induces cell proliferation, differentiation, migration, invasion, and EMT, promoting tumourigenesis and tumour progression." (PMID 34976187, 2022). "They express a variety of factors stimulating tumor growth such as epithelial growth factor (EGF), hepatocyte growth factor (HGF) or epithelial growth ligands of the factor receptor (EGFR) family." (PMID 35741108, 2022). "This occurs through CRC derived carcinoma-associated fibroblast (CAFs), as one of the components of TME, which up-regulates CD44 by HGF/C-MET pathway and promote adhesion and migration of CRC tumor cells in metastatic animal model by HGF secretion." (PMID 35590367, 2022). "HGF was shown to be produced by stromal cells in co-culture with HB cells, suggesting a paracrine mechanism of HGF stimulation, while analysis of tumor sections revealed high expression of c-MET by epithelial tumor cells." (PMID 36034555, 2022). "Neutrophils and macrophages secrete tumour-growth-promoting factors, including VEGF, HGF, IL-6, IL-8, MMPs, and elastases." (PMID 36077723, 2022). "TANs also play a role in tumor invasion and angiogenesis in primary and metastatic sites by generating MMP9, VEGF, HGF, PAF, IL-10." (PMID 36419156, 2022). "Neutrophil-derived hepatocyte growth factor (HGF)-/mesenchymal–epithelial transition factor (MET)-dependent NO can promote the killing of cancer cells, which abates tumor growth and metastasis." (PMID 36230676, 2022). "MMP9 not only contributes to the degradation of ECM but also to the release of hepatocyte growth factor, VEGF, and enhances tumor cell tolerance to stimulate tumor cell metastasis and angiogenesis." (PMID 36364935, 2022). "This pathway was shown to contribute to tumor resistance to MET TKI; stromal HGF and tumor MCT4 were also upregulated in epidermal growth-factor receptor TKI-resistant tumors of NSCLC patients." (PMID 35565690, 2022). "The CELsignia test was performed on cell samples cultured from each patient tumor specimen to evaluate HER-family and c-Met signaling activity applying EGF, NRG, and HGF agonists." (PMID 34998412, 2022). "We detected the expressions of c-MET and HGF in the tumor tissues and paracancerous tissues and found much higher expressions of c-MET and HGF in tumor tissues than in the paracancerous tissues (P < 0.01)." (PMID 35874635, 2022).
tumor (continued). "Dysregulation of hepatocyte growth factor/mesenchymal-epithelial transition factor gene (HGF/c-MET) pathway plays a crucial role in human carcinogenesis, tumor progression and resistance to antineoplastic treatments." (PMID 36498560, 2022). "In HCC, HGF is expressed by stromal cells or tumor cells and binds to its specific receptor, c-MET, to play a part in tumor onset, proliferation, invasion and metastasis." (PMID 36109787, 2022). "Further studies revealed that PTPRJ is involved in the hepatocyte growth factor (HGF) tyrosine kinase receptor c-Met, which affects the pro-tumor capacity of p38." (PMID 36611803, 2022). "Sorafenib inhibits angiogenesis, resulting in hypoxia inside tumors, which in turn increases the production of hepatocyte growth factor (HGF) and expression of c-MET in tumor cells." (PMID 35546143, 2022). "This pathway plays an important role in angiogenesis and tumor growth, with a synergistic action by HGF and VEGF on endothelial cells and also an increasing expression of angiogenic factors mediated by HGF." (PMID 36212393, 2022). "Aberrant activation of hepatocyte growth factor (HGF) and its receptor c-Met axis promotes tumor growth." (PMID 36012373, 2022). "Malignant ascites contains various metastasis-promoting mediators, produced by both tumor cells and CAFs, such as TGF-β1, HGF, GRO-1 and IGF-1." (PMID 35682890, 2022). "In NSCLC sufferers, their serum and tumor samples comprised elevated quantities of STAT3-driven cytokines IL-6/11/22 and leptin and HGF growth factors." (PMID 36497125, 2022). "Accumulated HGF can activate the HGF/c-Met, ERK1/2/MAPK, and PI3K/AKT pathways in tumor cells, recruit more M2 TAMs, and promote tumor growth." (PMID 36457492, 2022). "Hepatocyte growth factor (HGF)/c-MET, placental growth factor (PIGF) and angiopoietins are other pro-angiogenic factors which have demonstrated important roles in tumor angiogenesis." (PMID 36012123, 2022). "Contrastingly, M2 macrophages facilitate tumor proliferation via expressing various growth factors such as VEGF, TGF‐β1, epithelial growth factor (EGF), and hepatocyte growth factor." (PMID 35612789, 2022). "The expression of HGF, cMET, and phospho-cMET in the normal mammary glands was elevated, accelerating BBC tumor progression compared with lean controls." (PMID 35563777, 2022). "The CD44v6 isoform is required for c-MET activation by hepatocyte growth factor (HGF, or scatter factor) and as such plays an essential role in triggering EMT at the invasive front where tumor cells are exposed to these TME-secreted factors." (PMID 36346211, 2022). "It is reported that MET, induced by tumor inflammatory stimuli such as TNF-α, is essential for neutrophil chemoattraction and cytotoxicity in response to its ligand hepatocyte growth factor (HGF)." (PMID 35784290, 2022). "ZEB1 regulates the expression of paracrine signals such as hepatocyte growth factor (HGF) and interleukin 6 (IL-6) in tumor cells and CAFs, highlighting that the ZEB1–CTGF axis plays a key role in regulating the network between tumor cells and CAFs." (PMID 35159011, 2022). "Of these, c-MET along with hepatocyte growth factor (HGF) activates RAS-ERK and PI3K-AKT pathways, strengthening tumour aggressiveness with poor prognosis." (PMID 36345011, 2022). "It binds to the ligand hepatocyte growth factor (HGF), activating the PI3K-AKT, STAT, SRC, and MAPK signaling pathways, resulting in tumor cell proliferation, invasion, and metastasis." (PMID 35954441, 2022). "Immature DC can be recruited to the TME by tumor-derived factors such as VEGF, HGF, b-defensin, CXCL8, and CXCL12." (PMID 36419156, 2022). "CT053 (free-base form of CT053PTSA) inhibited MET, AXL, VEGFR2, FLT3 and MERTK phosphorylation and suppressed tumor cell angiogenesis by blocking VEGF and HGF, respectively, in vitro." (PMID 36341335, 2022).
tumor (continued). "High levels of HGF correlated with worse survival of TNBC patients, which might indicate the importance of the stromal effect on the disease course and underlines the importance of further research on the tumor microenvironment and its role in the progression of cancer." (PMID 35454913, 2022). "The authors demonstrated in a murine model that the inhibition of the HGF/c-MET axis impaired the recruitment of immunosuppressive neutrophils into tumors, thus allowing T cell tumor infiltration and enhancing the effect of immunotherapy." (PMID 36010840, 2022). "c-MET homodimerisation occurs following the binding of the hepatocyte growth factor (HGF) ligand, and RTK-mediated signalling leads to tumour proliferation and metastasis." (PMID 35144591, 2022). "At 3dpf, we find that centralized nodes include tumor-relevant pathways such as UVC-Induced MAPK Signaling and HGF Signaling." (PMID 34983392, 2022). "On the other hand, there are fewer reports suggesting a tumor-suppressive role of CAFs via the I kappa B kinase/NF-κB pathway, which leads to reduction of hepatocyte growth factor (HGF) secretion and reduction of tumor size and metastasis." (PMID 36544698, 2022). "There was an upregulation of HGF and MMP-2 in activated fibroblasts and CAFs compared to the control, suggesting their key role in the adhesion of tumor cells." (PMID 35682890, 2022). "Preclinical models have also correlated RFA-induced increases of inflammatory cytokines IL-6, HGF, and VGEF, to upregulation of downstream key proliferative pathways, and resultant accelerated distant tumor growth peaking 6h to 3d following ablation." (PMID 35857766, 2022). "Moreover, neutrophils belong to the main cytokine sources, such as interleukin 6, hepatocyte growth factor, transforming growth factor-β, interleukin 8, and matrix metalloproteinases and they are the factors which play an important role in different stages of tumour development." (PMID 35743468, 2022). "CAFs are further able to aid tumor invasiveness by promoting EMT of tumors cells through paracrine signaling, as TGFβ–SMAD, stroma-derived factor-1 (SDF1), and hepatocyte growth factor (HGF)." (PMID 36077813, 2022). "Neutrophils secrete tumor growth factors, including VEGF and hepatocyte growth factor (HGF), but also MMPs and elastases, and thus likely contribute to a pro-tumor TIM." (PMID 36294305, 2022). "Immune checkpoints (ICPs) (e.g., PD1 and PDL1) and immunogenic cell death modulators (e.g., HGF and IFN) are crucial for modulating the immune responses of effectors and maintaining the self-tolerance of tumor to minimize tissue damage." (PMID 35185876, 2022). "Immunohistochemistry also further demonstrated a high expression of c-MET in tumor tissues of the PSC and HGF groups." (PMID 35693705, 2022). "Functionally, short-hairpin RNA KD of CD151 strongly reduced HGF-induced ERK1/2 phosphorylation and tumour growth." (PMID 36330337, 2022). "Many osteoclast-activating factors (IL-6, IL-1β, HGF and TNF-α) are released by the mutual interactions of tumour and bone marrow cells with a major involvement of RANKL, the decoy receptor OPG, and MIP-1α a." (PMID 36362718, 2022). "We next examined the expression of RTK ligands, including HGF, EFNA5, and VEGFA, in the membranes of tumor cells." (PMID 35205843, 2022). "Radiofrequency ablation (RFA) of intrahepatic tumors induces distant tumor growth through activation of interleukin 6/signal transducer and activator of transcription 3 (STAT3)/hepatocyte growth factor (HGF)/tyrosine-protein kinase Met (c-MET) pathway." (PMID 35857766, 2022). "A PPI network of the selected 18 genes was constructed based on the STRING database, indicating the broad functional overlap between IL27 and IFN-γ, and interaction in remodeling the tumor immune microenvironment between IFN-γ and HGF." (PMID 36713514, 2022).
tumor (continued). "For example, tumor infiltrating myeloid cells release growth factors, such as epidermal growth factor (EGF), hepatocyte growth factor (HGF), and fibroblast growth factor (FGF)." (PMID 36426359, 2022). "HIF-1 can stimulate the hepatocyte growth factor (HGF)/HGF receptor (c-MET) signaling pathway, boosting tumor cell invasion and metastasis." (PMID 36591450, 2022). "HGF/MET interaction is frequently committed in human gliomas and high levels of these molecules correlate with high tumor grade and poor prognosis." (PMID 35069735, 2022). "Osteoblasts can promote tumor cell growth by expressing osteoprotegerin (OPG) and hepatocyte growth factor (HGF)." (PMID 36230816, 2022). "TAMs produce a variety of molecules that promotes tumor angiogenesis and stimulates tumor cell growth, such as VEGF, IL-1, hypoxia-inducible factor-2α, fibroblast growth factor and hepatocyte growth factor." (PMID 32624372, 2022). "When activated HGF binds to the c-Met receptor on tumor cells, it activates several signaling pathways, including MAPK, PI3K/AKT, and STAT3, which promotes tumor growth and therapeutic resistance." (PMID 36071472, 2022). "In vitro, cMET/HGF signaling induces FAK/MAPK/STAT signaling pathways and regulates tumor cell growth invasion." (PMID 36761417, 2022). "Hepatocyte growth factor receptor (c-Met) is a receptor for hepatocyte growth factor (HGF), which regulates tumor cell growth, invasion, metastasis, and angiogenesis." (PMID 36362345, 2022). "In Hepatic Stellate cell (HSC) cells, cytokines such as IL-6 and TNF promote the binding of HDAC7 to the anti-tumor gene cylindromatosis (CYLD), which recruits HDAC7 to the nucleus near the promoter of the hepatocyte growth factor (HGF)." (PMID 36148005, 2022). "In our present study, bioinformatics analysis and experimental method verification were used in combination to confirm that miR-495 directly targeted HGF and c-MET mRNA in CRC cells as well as in cetuximab-treated CRC patients whose tumours had progressed." (PMID 34976187, 2022). "The analysis showed a decrease of overall survival and indicated poor prognosis when SDF-1, HGF and VEGF-A were highly expressed in tumor tissues." (PMID 35328253, 2022). "By isolating exosomes from tumor tissues, we noticed that the CD63 and the PD-L1 in the HGF NPs group was barely visible, suggesting the remarkable inhibition of GW4869 to the tumoral exosome and exosomal PD-L1." (PMID 34593794, 2021). "For example, CAFs were shown to secrete high levels of hepatocyte growth factor (HGF), which activates its cognate receptor, c-Met kinase, on cancer cells, promoting tumor development." (PMID 34769066, 2021). "HGF and MIF were also upregulated in HCC tissues compared with those in para-tumor tissues, and predicted poor prognosis of HCC patients." (PMID 33658044, 2021). "Binding of HGF to c-MET activates the tyrosine kinase activity of c-MET, which promotes the proliferation, metastasis, and invasion of various tumor cells." (PMID 34408780, 2021). "In addition, blocking GCMSCs-derived HGF could decrease tumor proliferation and metastasis in vivo." (PMID 33718248, 2021). "Rigid ECM stimulates MSCs in the TME to secrete hepatocyte growth factor (HGF) and tenascin C, factors that promote tumor proliferation and transform into invasive phenotypes." (PMID 34957091, 2021). "The most key triggering factors of angiogenesis in a tumor tissue include MMPs, vascular endothelial growth factor-A (VEGF-A), fibroblast growth factor (FGF), hepatocyte growth factor (HGF), and PlGF." (PMID 33685452, 2021). "These cells hold significant influence over tumor ECs through the wide range of secretory factors including IL-1β, VEGF, FGF2, TGFα, hepatocyte growth factor (HGF), and angiopoietin 1 (ANG1)." (PMID 34987525, 2021). "The authors reported that this radiopharmaceutical selectively accumulated in tumors with high levels of HGF protein, including the U87MG GB tumor model in vivo." (PMID 34209513, 2021).